ZIC3 (Zic family zinc finger 3)
Description:
Acts as a transcriptional activator. Required in the earliest stages in both axial midline development and left-right (LR) asymmetry specification. Binds to the minimal GLI-consensus sequence 5'-GGGTGGTC-3'.
Synonyms: ZNF203; HTX; HTX1; VACTERLX
Tractability: PROTAC: UniProt records ubiquitination sites on it.
Gene: Protein-coding gene on chromosome X (137,563,314 to 137,577,691, forward strand). Ensembl gene ENSG00000156925.
Subcellular location: Nucleus; Cytoplasm
Subcellular location (Human Protein Atlas): Nucleoplasm
Pathways (Reactome):
Developmental Biology: POU5F1 (OCT4), SOX2, NANOG activate genes related to proliferation; Transcriptional regulation of pluripotent stem cells
Gene Ontology:
Molecular function: DNA-binding transcription activator activity, RNA polymerase II-specific; DNA-binding transcription factor activity; protein binding; RNA polymerase II cis-regulatory region sequence-specific DNA binding; sequence-specific DNA binding; sequence-specific double-stranded DNA binding; DNA-binding transcription factor activity, RNA polymerase II-specific; chromatin DNA binding; promoter-specific chromatin binding; RNA polymerase II transcription regulatory region sequence-specific DNA binding; transcription coactivator activity
Biological process: determination of digestive tract left/right asymmetry; determination of left/right symmetry; determination of liver left/right asymmetry; determination of pancreatic left/right asymmetry; heart looping; lung development; positive regulation of transcription by RNA polymerase II; central nervous system development; positive regulation of DNA-templated transcription; atrial cardiac muscle tissue development; axial mesoderm development; central nervous system segmentation; cranial skeletal system development; determination of left/right asymmetry in nervous system; embryonic pattern specification; face development; forebrain development; gastrulation; gene expression; germ-line stem cell population maintenance; heart development; hippocampus development; left/right axis specification; left/right pattern formation; limb morphogenesis; and 14 more
Cellular component: nucleoplasm; cytoplasm; nucleus
Homologues: Orthologues: chimpanzee ZIC3 (99% identical), macaque ZIC3 (99% identical), mouse Zic3 (98% identical), dog ZIC3 (98% identical), pig ZIC3 (98% identical), rabbit ZIC3 (98% identical), rat Zic3 (98% identical), tropical clawed frog zic3 (76% identical), zebrafish zic3 (75% identical), guinea pig ZIC3 (52% identical). Paralogues in human: ZIC2 (68% identical), ZIC1 (65% identical), ZIC5 (47% identical), ZIC4 (42% identical), GLI2 (33% identical), GLI3 (31% identical), GLIS3 (27% identical), GLI1 (26% identical), GLIS2 (25% identical), ZXDA (23% identical), ZXDB (23% identical), GLIS1 (22% identical), and 2 more.
Diseases named in the same sentence as ZIC3 in open-access papers:
ZIC3 is named in the same sentence as 49 diseases in open-access papers, as found by Europe PMC text mining. Sharing a sentence is not in itself a finding about the gene and the disease. The quoted sentences say what the papers report.
congenital heart disease (5 papers, 2011 to 2022). A heart disease that is present at birth. "Mutations in ZIC3 have been found in X-linked heterotaxy syndrome and isolated congenital heart disease (CHD)." (PMID 32243438, 2020). "Loss of function of the transcription factor ZIC3 causes X-linked heterotaxy and isolated congenital heart malformations and represents one of the few known monogenic causes of congenital heart disease." (PMID 21858219, 2011). "Mutations in the gene encoding zinc finger of the cerebellum protein 3 (ZIC3; NM_003413.3) result in heterotaxy and can cause isolated congenital heart defects (CHD)." (PMID 21858219, 2011). "ZIC3, a zinc-finger transcription factor member of the GLI superfamily, causes X-linked HTX and congenital heart disease in humans." (PMID 36085154, 2022).
glioma (4 papers, 2021 to 2024). A benign or malignant brain and spinal cord tumor that arises from glial cells (astrocytes, oligodendrocytes, ependymal cells). "The neural development-associated TFs, ZIC1, ZIC2, and ZIC3, were specifically expressed in glioma." (PMID 39345334, 2024). "Inflammatory microglial cells, dendritic cells, myeloid cells, and glioma stem cells were highly expressed in GBM tissue, and ACP7, EPPK1, PCDHA8, RHOD, DRC1, ZIC3, and PRLR were significantly associated with survival." (PMID 36836422, 2023). "Pathways such as Neuroactive ligand-receptor interaction were found to be regulated by ZIC3 in glioma patients." (PMID 34475426, 2021). "Taken together, our results showed that the gene expression of ZIC1 and ZIC3 were obviously different between glioma and normal samples, and the evidence of gene protein expression was not sufficient which needed further experimental verification.." (PMID 34475426, 2021). "In addition, lower protein expression of ZIC3 was identified in malignant high-grade glioma tissues compared with normal samples." (PMID 34475426, 2021). "For Zic3, it has been reported to be hypomethylated in cryptogenic HCC and a decreased expression has been identified in malignant high-grade glioma tissues when compared to the counterpart healthy tissue, implying a potential role during immortalization." (PMID 39125691, 2024). "After exploring the immune cell infiltration of ZICs in glioma patients, functional enrichment analysis were construct using the genes that were coexpressed with ZIC1/5 and ZIC3 in LGG and GBM, individually." (PMID 34475426, 2021).
atrial septal defect (2 papers, 2014 to 2021). Interauricular communication is a congenital malformation characterized by a communication between the atrial chambers of the heart. "Other potentially involved genes (GATA Binding Protein 4, GATA4; T-Box Transcription Factor 20, TBX20; NK2 Homeobox 5, NKX2-5; Zic Family Member 3, ZIC3) were initially recognized as pathogenic for Atrial Septal Defects (ASD)." (PMID 34946902, 2021).
cardio-facio-cutaneous syndrome (2 papers, 2021 to 2025). "TAPVD has been found in conjunction with several genetic syndromes, including mutations in GATA4 and ZIC3, as well as cardiofaciocutaneous syndrome, Holt-Oram syndrome, Williams syndrome, and cat-eye syndrome, suggesting a possible genetic predisposition." (PMID 40780769, 2025).
primary ciliary dyskinesia (2 papers, 2021 to 2025). A rare, genetically heterogeneous, primarily respiratory disorder characterized by chronic upper and lower respiratory tract disease. "Given the fact that other causes of heterotaxy such as variants in ZIC3 or in genes causing primary ciliary dyskinesia or other ciliopathies require molecular testing to identify, many of these patients had additional molecular testing." (PMID 34440418, 2021). "Genetic mutations (DNAH5, DNAI1, and ZIC3) have been linked to the development of SIT, particularly in association with primary ciliary dyskinesia (PCD)." (PMID 40772152, 2025).
seminoma (2 papers, 2015 to 2016). A radiosensitive malignant germ cell tumor found in the testis (especially undescended), and extragonadal sites (anterior mediastinum and pineal gland). "Furthermore, additional EC and pluripotency genes were upregulated (SOX2, LEFTY1 /2, DNMT3L, SALL4, DPPA5, BCAT1, FZD7, LIN28, ZIC3), while seminoma-associated genes where downregulated (SOX17, TFAP2C, cKIT, PRAME), without changing 5mC-levels." (PMID 26226633, 2015). "Furthermore, expression of ZIC3 is higher in EC tissues than in seminomas, CIS or normal testis tissue." (PMID 26226633, 2015). "ZIC3, which is necessary for maintenance of NODAL signaling is highly expressed in ECs /xenografted TCam-2 and low in seminomas /TCam-2 in vitro." (PMID 26226633, 2015). "Among them, GDF3, NODAL, LEFTY1 /2, GAL, DPPA3, SOX2, DNMT3B /L, DPPA5, BCAT1, FGF2, PRDM14, ZIC3 and FZD7, while seminoma markers SOX17, cKIT and PRAME were downregulated." (PMID 26226633, 2015). "Additionally, many pluripotency and EC associated genes, like SOX2, ZIC3, ZFP42, LIN28, SALL4 and PRDM14 were upregulated without correlating to changes in their 5mC status, while seminoma markers SOX17, cKIT, PRDM1 and PRAME were downregulated." (PMID 27283990, 2016). "Furthermore, we postulated that during the seminoma to EC transition, inhibition of BMP signaling leads to derepression of SOX2, restoring the classical pluripotency circuitry found in ECs and ESCs, subsequently leading to upregulation of ZIC3, which in turn helps to maintain NODAL signaling." (PMID 27283990, 2016).
spina bifida (2 papers, 2010 to 2025). A congenital neural tube defect in which vertebrae are not fully formed. "Only one embryo displayed spina bifida (data not shown), indicating that the addition of the V5 epitope tag was not interfering with the function of ZIC3." (PMID 39912332, 2025). "Zic2/Zic3 double mutants exhibit craniorachischisis though this may be a result of exencephaly and severe spina bifida, rather than a failure of closure 1; genetic interaction between Zic mutants and the PCP pathway has not been assessed." (PMID 20704721, 2010).
aneurysm (1 paper, 2021). Bulging or ballooning in an area of an artery secondary to arterial wall weakening. "Furthermore, miR-155-5p inhibited the viability of vascular smooth muscle cells and promoted the formation of aneurysms by targeting Fos and ZIC3." (PMID 34638868, 2021).
Anophthalmia (1 paper, 2022). Absence of the globe or eyeball. "The disease locus was reported to be situated close to Bent tail (Bn) (since mapped to a loss of function mutation for Zic3), and between Greasy (Gs), and sparse fur (Spf) on chromosome X. Males and homozygous females displayed anophthalmia and malformations of the external ear." (PMID 36292683, 2022).
asthma (1 paper, 2014). "However, further experimental verification is needed on the possible roles of HAND1, PTK7, and ZIC3 in asthma proposed in this study." (PMID 24790987, 2014). "Our results highlight a role of Zic3 in the maintenance of asthma." (PMID 24790987, 2014). "We suggested that HAND1, PTK7, and ZIC3 may be used as biomarkers for asthma; however, more work is needed to validate our result." (PMID 24790987, 2014). "In addition, HAND1, PTK7, and ZIC3 were found to be potential asthma-related factors considering their TIF values." (PMID 24790987, 2014).
bile duct obstruction (1 paper, 2022). "Third, the inv mice model with bile duct obstruction and situs inversus with DPM and the findings of mutations in laterality genes (CFC1, ZIC3) in some patients with BA and laterality defects together underlines the role of morphogenetic defects in bile duct malformation." (PMID 35887185, 2022).
brain tumors (1 paper, 2010). "We examined the mRNA and protein expression of human ZIC1, ZIC2, ZIC3, ZIC4 and ZIC5 genes in meningiomas in comparison to other brain tumors, using RT-PCR, analysis of published microarray data, and immunostaining." (PMID 20199689, 2010). "However, the expression of the other ZIC genes (ZIC2, ZIC3, ZIC4, and ZIC5) has not been investigated in medulloblastoma or other brain tumors." (PMID 20199689, 2010).
dementia (1 paper, 2025). Loss of intellectual abilities interfering with an individual's social and occupational functions. "Therefore, the identification of Zic3 as a BBB endothelial cells marker will likely advance our studies towards a better understanding of BBB vascular cell changes in aging and CNS diseases, including vascular contributions to AD and dementia." (PMID 40909791, 2025).
gastric cancer (1 paper, 2020). A primary or metastatic malignant neoplasm involving the stomach. "Some members of the ZIC family has been reported as tumor suppressor in gastric cancer including ZIC3." (PMID 32390766, 2020).
glioblastoma (1 paper, 2021). The most malignant astrocytic tumor (WHO grade IV). "The mRNA expression of ZIC1 were highly expressed in glioblastoma patients, and ZIC3 and ZIC4 were downregulated expression." (PMID 34475426, 2021). "High expression levels of ZIC1/5 were associated with poor OS in brain low-grade glioma (LGG) patients, while low ZIC3 expression combined was related to favorable OS in glioblastoma multiforme (GBM)." (PMID 34475426, 2021).
high-grade glioma (1 paper, 2023). "In particular, ZIC3 was associated with longer survival, which is consistent with previous studies that have shown that ZIC3 was downregulated in malignant high-grade glioma." (PMID 36836422, 2023).
Infertility (1 paper, 2024). "Other etiological possibilities are a diabetic mother, a baby born out of infertility treatment, and exposure to lead, anticonvulsants, estrogen or progesterone-containing compounds, or alcohol during the period of embryogenesis causing mutations in the genes like HOXD13, FOXF1, and ZIC3." (PMID 39463584, 2024).
meningioma (1 paper, 2010). A generally slow growing tumor attached to the dura mater. "The ZIC3 and ZIC4 mRNA levels were higher in meningioma than in whole brain in one out of the three cases." (PMID 20199689, 2010).
oral cancers (1 paper, 2024). "This analysis revealed that in addition to the positive control GAPDH, all oral cancers (except SCC4) upregulated the miR-155 downstream targets OLFML3, TBR1, BACH1, ZNF652, IRF2-BP2, and ZIC3." (PMID 38396844, 2024).
teratocarcinoma (1 paper, 2011). A germ cell tumor characterized by the presence of an embryonal carcinoma component and a teratoma component. "Both Zic3 transcript isoforms were also detected in human embryonic kidney (HEK293) and pluripotent murine teratocarcinoma (P19) cells." (PMID 21858219, 2011).
tumor (6 papers, 2016 to 2025). "At the time of diagnosis, the tumor cells had four distinct SNVs in USP54, GABRA3, KRAS and SETD2, while the relapsed tumor acquired four additional unique mutations in MYH7, NYNRIN, ODZ1 and ZIC3." (PMID 26527318, 2016).
cancer (2 papers, 2022 to 2023). A tumor composed of atypical neoplastic, often pleomorphic cells that invade other tissues. "Moreover, CD11A, ZNF278, VDR, ZIC3, and NFκB also play critical roles in the modulation of oncogenic processes in many type cancers." (PMID 35456435, 2022).
cardiovascular disease (1 paper, 2021). "In conclusion, TEAD2, TEAD4 and ZIC3 can increase the efficiency of reprogramming human urine cells into iPSCs, and provides a new stem cell sources for the clinical application and modeling of cardiovascular disease." (PMID 34448118, 2021).
ZIC3 also shares sentences with these, for which no sentence is quoted: Hydrocephalus (2 papers); asplenia syndrome (1); astrocytic tumor (1); breast carcinoma (1); cat-eye syndrome (1); ciliopathies (1); congenital heart defects (1); congenital heart malformations of (1); Costello syndrome (1); craniorachischisis (1); Dextrocardia (1); DiGeorge syndrome (1); ependymal tumor (1); Heterotaxy (1); holoprosencephaly (1); Holt-Oram syndrome (1); lung carcinoma (1); Noonan syndrome (1); Pettigrew syndrome (1); RASopathies (1); situs inversus (1); Situs inversus totalis (1); VACTERL-H (1); ventricular septal defect (1); visceral heterotaxy (1); Williams syndrome (1).